INS (insulin)
Diseases named in the same sentence as INS in open-access papers (continued):
Sharing a sentence is not in itself a finding about the gene and the disease.
type 2 diabetes (continued). "Type 2 diabetes mellitus (T2DM) is the most common human endocrine disease and is characterized by peripheral insulin resistance and pancreatic islet β-cell failure resulting fat deposition in adipose tissue." (PMID 28540446, 2017). "Interestingly, physical exercise improves glucose uptake by skeletal muscle resulting in improved insulin sensitivity, an effect that is partially mediated by an increased BK concentration, suggesting a mechanism by which physical exercise would contribute to the prediction of type 2 diabetes." (PMID 28597074, 2017). "GLP-1R is initially found expressing in pancreatic islets cells and activated GLP-1R induces insulin synthesis and release; thus, GLP-1R agonists or dipeptidyl peptidase 4 (DPP-4) inhibitors have been used in the treatment of type 2 diabetes mellitus (T2DM)." (PMID 28846606, 2017). "In a recent study in individuals with type 2 diabetes we studied the effect of cold acclimation on BAT activity and insulin sensitivity using hyperinsulinaemic–euglycaemic clamp." (PMID 27591854, 2016). "G protein-coupled receptor 40 (GPR40) contributes to medium- or long-chain fatty acid-induced amplification of glucose-stimulated insulin secretion (GSIS), and GPR40 agonists are promising therapeutic targets in type 2 diabetes." (PMID 27180622, 2016). "In patients with type 2 diabetes basal insulin therapy is usually initiated with the conventional NPH (neutral protamine Hagedorn) insulin, or a newer, longer-acting basal insulin analogue detemir or glargine." (PMID 27031113, 2016). "Similar to the obese condition, also healthy lean first-degree relatives of type 2 diabetic patients exhibit higher plasma fatty acid and IMTG concentration and a lower insulin sensitivity." (PMID 27777958, 2016). "In type 2 diabetes patients, despite a normal amount of GLUT4 transporters, insulin fails, in general, to induce adequate insulin signaling as assessed by IRS-1 tyrosine phosphorylation, Akt/PKB activity, and translocation of GLUT4 to the cell membrane." (PMID 27069930, 2016). "In the present study, we investigated the association of the serum amylase levels with insulin secretion, insulin sensitivity and integrated islet β cell function derived from the OGTT in a large Chinese population with early type 2 diabetes." (PMID 27606813, 2016). "In an animal models of type-2 diabetes, treatment with an antisense oligonucleotide specific for PTP1B results in improvement of hyper glycaemia and insulin sensitivity." (PMID 26808535, 2016). "T2D, also called non-insulin-dependent diabetes (NIDDM), is characterized by hyperglycemia resulting from impairment of insulin secretion and/or defects in insulin action in peripheral tissues." (PMID 27573367, 2016). "As an intermediate state between normal glucose tolerance (NGT) and type 2 diabetes (T2DM), pre-DM is characterized by insulin resistance and impaired insulin secretion." (PMID 27738641, 2016). "However, in type 2 diabetes (T2D) pancreatic β-cells fail to compensate for an increase in blood glucose concentration with sufficient insulin secretion, leading to progressive hyperglycemia." (PMID 27138453, 2016). "Insulin and C-peptide levels were decreased by fish and meat preload in type 2 diabetes and healthy individuals, despite enhanced secretions of GIP and GLP-1 that should stimulate insulin secretion glucose-dependently." (PMID 26704625, 2016). "Moreover, whether LCHFDs will prove beneficial for improving glucose control in type 2 diabetes after long-term use will depend on their impact on glucose-induced insulin secretion from pancreatic β-cells, which prior to this study has not been carefully examined." (PMID 26878317, 2016). "Dipeptidyl peptidase IV (DPP-4) enzyme is responsible for the degradation of incretins that stimulates insulin secretion and hence inhibition of DPP-4 becomes an established approach for the treatment of type 2 diabetics." (PMID 27832184, 2016).
type 2 diabetes (continued). "It is well known that RAS inhibitors, ACEI or ARB, can increase insulin sensitivity and diminish MAU in type-2 diabetes." (PMID 27164093, 2016). "However, when insulin secretion/insulin sensitivity is impaired, an increase in insulin resistance is triggered, inducing gestational diabetes mellitus (GDM) which in turn is linked to high birth weight, early onset of obesity, and type 2 diabetes in adulthood." (PMID 27087124, 2016). "Indeed, small clinical studies in type 2 diabetes have demonstrated that improved metabolic control may enhance myocardial perfusion and function and that short-acting analogue insulin normalizes myocardial perfusion in the postmeal state by 35 % when compared to being left untreated." (PMID 26772807, 2016). "Regarding type 2 diabetes mellitus (T2DM), patients are heterogeneous in terms of weight, insulin sensitivity, beta cell function and renal and liver function." (PMID 27789671, 2016). "Along with our previous observation of increased fasting blood glucose in HFD-fed males, serum insulin concentrations were also significantly elevated in HFD-fed males compared to CD-fed males (p = 0.02), both clinical indicators of type-2 diabetes." (PMID 26823968, 2016). "Type 2 diabetes mellitus (T2DM) makes up about 90% of all cases and is caused by a combination of inadequate compensatory insulin secretion and a lack of functional insulin receptors, termed insulin resistance." (PMID 26820984, 2016). "The UKPDS, a study in patients newly diagnosed with type 2 diabetes, suggested a CVD benefit in those individuals randomized to an intensive policy using oral glucose-lowering medications or insulin, compared to those who received the conventional policy." (PMID 27188479, 2016). "On the other hand, we found a robust association between elevated chemerin and increased beta-cell function which points towards a novel beneficial role of chemerin for dynamic insulin secretion in the context of NAFLD and type 2 diabetes." (PMID 25933030, 2015). "As IDE demonstrates an ability to degrade insulin, amylin, and Aβ, it has been suggested that IDE is a candidate gene for both type 2 diabetes and AD." (PMID 26173052, 2015). "In fact, patients on sitagliptin monotherapy had the shortest history of type 2 diabetes among groups (8.66 years for sitagliptin monotherapy, 11.8 years for sitagliptin-SU group and 11.2 years in sitagliptin-other OHA and/or insulin group)." (PMID 25699116, 2015). "Previous studies in patients with type 2 Diabetes and metabolic syndrome have observed an inverse correlation of fasting blood glucose with CTRP3, and a study in women with PCOS found insulin to be an independent predictor of CTRP3." (PMID 26222183, 2015). "It is a retrospective cohort study involving data of type 1(DM1) and type 2 diabetes (DM2) patients 18 years old and above who were registered to participate at the insulin analogues dispense program of the SHS-FD." (PMID 26288660, 2015). "The extensive literature indicating the ability of acute and chronic alcohol intake to often times antagonize insulin-stimulated glucose disposal in peripheral tissues and the suppression of hepatic glucose production might be anticipated to exacerbate the development of type 2 diabetes mellitus." (PMID 26426068, 2015). "l-glutamine triggers glucagon-like peptide-1 (GLP-1) release from L cells in vitro and when ingested pre-meal, decreases postprandial glycaemia and increases circulating insulin and GLP-1 in type 2 diabetes (T2D) patients." (PMID 25811109, 2015). "The need for insulin characterizes patients with a more severe form of GDM, who will have an increased probability of developing type 2 Diabetes Mellitus (T2DM) and cardiovascular complications in the future." (PMID 26633694, 2015). "The effects of twice-daily GLP-1 analogue injections added on continuous subcutaneous insulin infusion (CSII) in patients with poorly controlled type 2 diabetes (T2DM) were unknown." (PMID 26607841, 2015).
type 2 diabetes (continued). "The levels of a number of insulin signaling molecules including IR, IRS-1, and PKB were significantly reduced in the post-mortem frontal cortex of individuals with both AD and type II diabetes." (PMID 26499801, 2015). "It should be noted that insulin is significant IGF 1 secretion promoter just like GH, and that patients with type I and some with type II diabetes receive insulin therapy as their standard treatment procedure." (PMID 26321025, 2015). "As a strong point, this study manages to enroll a significant amount of rather homogenous patients, very likely to represent the “real life” type 2 diabetes patients, treated with OGLD only, who come to the point of insulin requirement." (PMID 26176017, 2015). "In addition, increased plasma levels of ApoC-III (an inhibitor of LPL) could also contribute to the decreased catabolism of VLDL in patients with type 2 diabetes, since increased plasma levels of ApoC-III were associated with impaired VLDL clearance in obese insulin-resistant men." (PMID 25725623, 2015). "Contrary to type 2 diabetes and despite to higher level of FBS and insulin, NWO patients had higher levels of irisin." (PMID 27354972, 2015). "Because PASK regulates insulin secretion in β cells, researchers have begun to study the connection between PASK and type II diabetes." (PMID 26371032, 2015). "In contrast to alpha-tocopherol, our finding demonstrated the effectiveness of ascorbic acid in reducing fasting insulin and HOMA-IR% in type 2 diabetes patients." (PMID 26693410, 2015). "A clinical trial investigating the effect of the FXR agonist INT-747 in patients with type 2 diabetes and non-alcoholic fatty liver disease, concluded that FXR activation improved insulin sensitivity and reduced markers of liver inflammation and fibrosis." (PMID 26583035, 2015). "Type 2 DM is adult-onset diabetes and is called as noninsulin dependent diabetes mellitus (NIDDM) which results from the body tissues and cells inability to respond properly to the action of insulin." (PMID 26273663, 2015). "In a cohort study with type 2 diabetes patients, oral administration of OSA (1 g/day, 60 days) induced significant increases in circulating insulin and C-peptide concomitant with a significant reduction in blood glucose levels." (PMID 26587047, 2015). "In type 2 diabetes patients, ingestion of l-glutamine prior to a meal increases circulating GLP-1, delays gastric emptying, increases circulating insulin and lowers postprandial glycaemia." (PMID 25811109, 2015). "In contrast with previous work by Lai (2008), ▶ our finding demonstrated the effectiveness of ascorbic acid alone in reducing fasting insulin and HOMA-IR% in type 2 diabetes patients." (PMID 26693410, 2015). "Using 1.5T MRI, we longitudinally imaged the changes in insulin content in male and female mice of the RIP-DTr strain, which mimic the changes expected in type 1 and type 2 diabetes, respectively." (PMID 25413047, 2015). "In noninsulin-dependent diabetes mellitus (NIDDM) or type 2 diabetes, muscle, liver, and fat cells become “resistant” to the actions of insulin." (PMID 25866533, 2015). "Many cancer patients with type 2 diabetes has metabolic and hormonal characteristics and the hyperproliferative processes of cancer cells could be suppressed by metformin or dietary protein restriction through insulin-independent and insulin-dependent mechanisms." (PMID 24810113, 2014). "Insulin plays a key role in these changes and also inhibits IGFBP-1: low levels predict the development of disturbances in glucose homeostasis including type 2 diabetes several years later." (PMID 26237614, 2014). "In the progression to type 2 diabetes, IGFBP-1 is less suppressed and is inappropriately high in relation to the prevailing insulin concentrations." (PMID 26237614, 2014).
type 2 diabetes (continued). "A number of GLP-1 analogs are being developed as pharmaceutical agents for the treatment of type-2 diabetes, as GLP-1 increases postprandial insulin secretion, suppresses postprandial glucagon secretion, and delays gastric emptying." (PMID 24847313, 2014). "In obese or type 2 diabetic animals, cardiac glucose uptake is reduced as a consequence of reduced GLUT4 protein and impaired insulin signaling." (PMID 26237391, 2014). "To determine the effect of CE on type 2 diabetes, we performed the oral glucose tolerance test (OGTT) and insulin tolerance test (ITT) in type 2 diabetes model rats in vivo." (PMID 24551069, 2014). "Within days after surgery, liver fat levels fell and normal hepatic insulin sensitivity was restored, arguing that NAFLD is a late step in the pathophysiology towards type 2 diabetes." (PMID 24632889, 2014). "Clinical study reported that vildagliptin in addition to metformin reduced fasting plasma insulin level and HOMA-IR in type 2 diabetic patients." (PMID 25036861, 2014). "Recently, it is suggested that cholesterol homeostasis plays an important role for beta-cells to perform adequate insulin secretion and low HDL cholesterol levels are normally related with hyperglycemia and type 2 diabetes." (PMID 25280459, 2014). "Type 2 diabetes (T2DM) is characterized by both insulin resistance and inadequate insulin secretion." (PMID 25145469, 2014). "In this study, we demonstrated a variety of PFAA profiles in type 2 diabetic patients and reported that the PFAA profiles and amino acid indices evaluating visceral obesity showed good correlations with insulin-related variables and adiponectin concentrations." (PMID 25177913, 2014). "While, Type 2 Diabetes (T2DM), the most common form of the disease, is characterized by defects in both insulin secretion from pancreatic β-cells and insulin sensitivity in peripheral tissues such as skeletal muscle, liver, and fat." (PMID 24409188, 2014). "Also, it was recently shown that mice exposed to 30 days CIH exhibited pancreatic β-cell dysfunction, manifested by impaired glucose-stimulated insulin secretion and increased mitochondrial ROS, which may contribute to the development of type 2 diabetes among sleep apnea patients." (PMID 25400585, 2014). "For example, the activity of the adiponectin gene, which codes for a hormone controlling insulin sensitivity, was previously shown to be suppressed by BPA, implicating BPA in the development of type 2 diabetes." (PMID 24433282, 2014). "Type 2 diabetes patients often develop some form of dementia (such as AD), whereas AD patients may also present hyperglycemia, hypercholesterolemia, and insulin signaling dysfunction (common features to T2D)." (PMID 25071725, 2014). "Accumulating clinical data show that SGLT2 inhibitors including empagliflozin reduces body weight in type 2 diabetic patients and glucose lowering action of SGLT2 inhibitors is insulin-independent." (PMID 25344694, 2014). "Vildagliptin alone or combined with oral hypoglycemic drugs or insulin has been demonstrated in numerous randomized controlled clinical trials to effectively reduce the FBG and HbA1c levels in patients with type II diabetes." (PMID 24926379, 2014). "We measured serum galectin-3 levels in type 2 diabetes patients, and performed a glucose clamp method and a meal tolerance test (MTT) to evaluate insulin resistance and beta cell function." (PMID 25302080, 2014). "It remains unknown whether DHA and AA may affect insulin sensitivity or beta-cell function during fetal life, and whether low circulating DHA or AA levels may be involved in perinatally “programming” the susceptibility to type 2 diabetes in the offspring of gestational diabetic mothers." (PMID 24454790, 2014).
type 2 diabetes (continued). "Type 2 diabetes (T2D) is a complex multifactorial disorder characterized by chronic hyperglycemia due to impaired insulin secretion from pancreatic β-cells, elevated glucagon secretion from pancreatic α-cells and insulin resistance in target tissues." (PMID 24603685, 2014). "Type 2 diabetes (T2DM) is a chronic, progressive disease characterized by insulin resistance and beta-cell dysfunction resulting in the decline of insulin production and secretion." (PMID 25408147, 2014). "Therapeutically, 80.1% of type 2 diabetes patients were on an oral anti-diabetic (OAD), 26.3% were on OAD and insulin and 19.6% were on insulin only." (PMID 24564974, 2014). "Add-on of sitagliptin to ongoing insulin therapy effectively reduced either HbA1c level or glucose fluctuation and could be a practical and well-tolerated alternative to treat Japanese patients with type 2 diabetes who had been inadequately controlled by insulin with or without other OHAs." (PMID 27419209, 2014). "Compared with the results of a same Chinese population-based study involving patients with type 2 diabetes, despite a lower HbA1c level (8.32% vs 7.85%), the PSQI global score was higher (6.33 vs 6.67) in patients using exogenous insulin." (PMID 23383010, 2013). "It is involved in glucose-stimulated insulin secretion and glucagon-like peptide-1 (GLP-1) release, thereby representing a promising target for the treatment of type 2 diabetes." (PMID 23704946, 2013). "The properties of GLP-1 on insulin secretion and β-cell proliferation make GLP-1 one of the most promising therapeutic agent to treat type-2 diabetes." (PMID 23641235, 2013). "Type 2 diabetes mellitus (T2DM), characteristic of defects in both insulin secretion and sensitivity, is an increasing threat to human health." (PMID 23704946, 2013). "Consistent with a pathogenic role in islets, it has recently been shown that JAZF1 expression is reduced in individuals with type 2 diabetes or hyperglycemia, and that JAZF1 expression was correlated with insulin secretion." (PMID 23442068, 2013). "We examined levels of adiponectin and its insulin-sensitising HMW isoform and their relationship with metabolic parameters in Tongans, a population prone to type II diabetes." (PMID 23936666, 2013). "However, when β-cells are unable to compensate for increased insulin demand, there is a decrease in β-cell mass characteristic of the onset of type 2 diabetes mellitus (T2DM)." (PMID 26904613, 2013). "However, the progressive nature of Type 2 diabetes and the inability of basal insulin to correct excessive postprandial glucose excursions mean that insulin therapy will eventually need to be intensified, typically by adding prandial insulin as part of a basal–bolus or premixed insulin regimen." (PMID 22998363, 2013). "The lack of responsiveness to cardiac insulin stimulation in the PRKAG2 mutant mice, where AMPK activity is dysfunctional, is intriguing where a link between insulin stimulation and AMPK is currently under investigation with regards to type 2 diabetes." (PMID 23829931, 2013). "Some of these hub proteins are the components of our identified enriched pathways, including calcium signaling, g-secretase mediated ErbB4 signaling, adipocytokine signaling, insulin signaling, AKT signaling and type II diabetes mellitus pathways." (PMID 23369358, 2013). "Insulin sensitivity is negatively correlated with obesity in type 2 diabetes, PF40 significantly increased the level of Acrp30 to promote adipocyte differentiation and fatty acid catabolism resulted that insulin was more sensitive." (PMID 24131482, 2013). "Orally administered sulphonylurea drugs, commonly used to treat type 2 diabetes, close the KATP channel by an ATP independent route and thus increase insulin secretion, although the required dose is frequently considerably higher." (PMID 24705260, 2013).